INS (insulin)
Diseases named in the same sentence as INS in open-access papers (continued):
Sharing a sentence is not in itself a finding about the gene and the disease.
Obesity (continued). "Estradiol might contribute to NEEC development directly through stimulation of estradiol responsive parts of heterogenic non-endometrioid tumors, or indirectly by obesity associated mechanisms such as alterations in the insulin metabolism or in the inflammatory response." (PMID 31174495, 2019). "From a physiological perspective focusing on obesity and its related metabolic diseases, hepatic PSAT1 has revealed a novel function in the regulation of insulin sensitivity." (PMID 31234367, 2019). "The pro-inflammatory state of obesity promotes IR and atherogenesis, thus in PCOS, the development of obesity induces a decline in insulin sensitivity." (PMID 31683535, 2019). "Robust metabolic phenotypes were observed in Adipoq-Lkb1 mice, such as improved systemic insulin sensitivity, glucose tolerance and energy expenditure, and resistance to HFD-induced obesity." (PMID 30318987, 2019). "Aside from the regulation of adipogenesis rate, study on murine liver cells revealed that overexpression of miR-143 disrupted insulin-dependent AKT activation, implying the involvement of this miRNA in obesity-induced IR." (PMID 31408957, 2019). "Administration of the muscarinic agonist bethanechol increased insulin secretion and improved glucose tolerance in insulin-receptor substrate 2 (IRS2)-knockout (IRS-2−/−) mice and diet-induced obesity mice." (PMID 31700039, 2019). "On the other hand, the genetic deletion of TIMP-2 in mice promotes HFD-induced obesity and diabetes and exercise has been reported to exert a positive effect in TIMP-2 modulation, improving insulin sensitivity." (PMID 31581657, 2019). "Previously, Eckel and colleagues studied a relatively homogenous population with obesity and T2D and found that MCT improved insulin sensitivity in patients who already have metabolic dysfunction in a monitored inpatient setting." (PMID 31869355, 2019). "By accounting for β-cell function, we were able to determine that the state of insulin and glucose metabolism is pertinent to striatal D2/3R BPND in obesity." (PMID 30849082, 2019). "We also evaluated some metabolic (leptin, insulin, glucose) and neuroendocrine and endocrine (Pomc and Npy expression, HPA axis) parameters related to diet-induced obesity and stress, some of which modulate the activity of TRH neurons in the PVN." (PMID 31354623, 2019). "In this study, obesity induced by HFD rats showed abnormal clinical manifestations such as hyperglycemia, hypertriglyceridemia, impaired glucose tolerance and impaired insulin resistance." (PMID 30902099, 2019). "Insulin sensitivity (as reflected by a decreased in fasting insulin and HOMA-IR) has been shown to be improved in children with obesity and hyperinsulinemia treated with metformin for 6 months." (PMID 31821361, 2019). "The knockout of miR-378 and miR-378* in mice resulted in enhanced mitochondrial fatty acid metabolism, elevated oxidative capacity of the target tissues of insulin, and increased resistance to HFD-induced obesity." (PMID 30304787, 2018). "This indicates that obesity or high-fat feeding may not be the main cause of elevated apelin, and implies that a close relationship exists between apelin and both the secretion and action of insulin." (PMID 30157220, 2018). "In particular, melatonin can improve insulin sensitivity through promoting mitochondrial functions of subcutaneous fat and skeletal muscle 46, 60, 61 and ameliorate hepatic steatosis via increasing hepatic glycogen content in the liver, which may benefit the obesity‐combined smokers." (PMID 29437243, 2018). "Plasma concentrations of insulin and leptin increased markedly with HFD-induced obesity (chow ad libitum vs. HFD ad libitum)." (PMID 30210452, 2018). "In another study, GDF15 transgenic mice were resistant to diet- and genetically induced obesity and exhibited improved insulin sensitivity due to a reduction in NLRP3 inflammasome activity in adipose tissue, in the context of obesity and insulin resistance." (PMID 29674655, 2018).
Obesity (continued). "Taken together our findings are consistent with elevated TCPTP in obesity perturbing POMC insulin responses and the proportion of POMC neurons activated versus inhibited by insulin to drive HGP and fasting hyperglycemia in obesity." (PMID 30230471, 2018). "Diet-induced obesity upregulates RAS in adipose tissue that increases reactive oxygen species, elevates lipogenesis, impairs insulin signaling, and promotes inflammation in the circulation." (PMID 29636702, 2018). "Recent studies have demonstrated that obesity leads to activation of the hepatic CB1R signaling, which contributes to insulin resistance and gluconeogenesis in the ER stress dependent manner, resulting in hyperglycemia." (PMID 29570673, 2018). "Furthermore, under hypertrophied and insulin resistant conditions, attenuated endocytosis of apoA5 by adipocytes may lead to excessive augmentation of TG storage and abnormal metabolism of adipocytes, which promotes the development of obesity." (PMID 30053818, 2018). "In PCOS OUH, age, obesity (BMI, waist), BP (systolic and diastolic), lipid status (LDL, cholesterol, TG), prolactin, blood glucose (fasting, 2 h), insulin (fasting, HOMA-ir) were significant predictors for development of CVD." (PMID 29519249, 2018). "In both obesity and fasting, insulin suppressed EGP indicating that, in contrast to muscle, hepatic sensitivity to insulin was preserved." (PMID 30183740, 2018). "Our data suggest that upregulation of gp130 signaling genes AT expression may be important for the weight loss-associated lipolysis in young subjects with uncomplicated obesity after moderate weight loss, however, they are not related to the concurrent improvement in insulin action." (PMID 29737494, 2018). "Therefore, on the basis of these information, it is evident that the decrease of DHEA levels may furtherly enhance the fat accumulation, thus generating a vicious circle in obesity and contributing to higher insulin concentrations and lower fertility in obese women." (PMID 29523133, 2018). "We also evaluated the plasma levels of different obesity and T2D markers such as adiponectin, leptin, resistin, visfatin, PAI-1, and insulin." (PMID 30131766, 2018). "When the correlation study was performed separately in relationship to obesity, it was found in lean girls that pro-UGN levels were negatively correlated with age, Tanner stage, weight, height, BMI, waist circumference, insulin leptin and testosterone." (PMID 30266914, 2018). "When molecular signaling pathways related to insulin signaling were examined in the liver, MLB supplementation suppressed ER stress- and inflammasome-related signaling molecules induced by aging and obesity." (PMID 30134566, 2018). "Although GLP-1R agonist increased insulin-stimulated glucose uptake in fat derived cells under normal condition, whereas the clinical indications of GLP-1 were obesity and obesity-related type 2 diabetes." (PMID 30459598, 2018). "These include factors existing before pregnancy such as pre-pregnancy weight and a family history of T2DM, factors which occurred during the index pregnancy such as the need to use insulin to control GDM, and postpartum factors such as obesity." (PMID 30186874, 2018). "Classified by sex, both in boys and girls, there were differences in fasting insulin and HOMA-IR between normal weight and obesity in all the Tanner stages (P < 0.05)." (PMID 30254673, 2018). "In states of obesity/DT2, when insulin production is upregulated, glucagon secretion should be downregulated, however, the opposite situation is observed, another aspect of the “enigma” concerning the mechanisms controlling glucagon secretion." (PMID 30293998, 2018). "Its phosphorylation at Ser401, which is downregulated in obesity, plays a key role in regulating the interaction of IR and IRS proteins, and thus insulin signaling." (PMID 30602666, 2018).
Obesity (continued). "Moreover, genetic deletion of protein-tyrosine phosphatase 1B in SF-1 neurons exacerbates diet-induced obesity in a sex-dependent manner that is associated with reduced sympathetic tone and energy expenditure in female but not male animals caused by enhanced insulin signaling in these cells." (PMID 29973869, 2018). "The free fatty acid derivatives released during lipolysis can serve as intrinsic ligands for PPARγ and can impair insulin-signaling; hence, the regulation of ATGL and HSL are important in relation to obesity, T2D, and related metabolic disorders." (PMID 30248999, 2018). "A possible explanation for the contradictory observations of insulin pathway activation in cellular level and animal level is the effects of ginsenoside Rg1 on insulin resistance and glucose uptake, which could be an indirect secondary effect to its anti-obesity function." (PMID 29513799, 2018). "Compared with controls, obese T2DM patients had higher systolic and diastolic blood pressure (P < 0.05), triglycerides and fasting insulin levels were higher in obese T2DM and obesity groups as compared to controls (P < 0.05)." (PMID 29654499, 2018). "IL-1β represents an insulin resistance-promoting adipokine with strong pro-inflammatory properties and AT expression is upregulated in HFD-induced obesity and insulin-resistant mouse models." (PMID 28932870, 2018). "Similar to the LPA1 downregulation in PGAT from mice with diet-induced obesity, LPA1 mRNA levels were reduced in insulin resistant (IR) vs. insulin sensitive (IS) adipocytes." (PMID 29236751, 2017). "This is an exciting feature of the association of reduced MEST and ATE with improved glucose/insulin metabolism because, unlike many other anti-obesity therapies, it provides encouragement that targeting the MEST pathway to reduce ATE may have a minimal number of side effects." (PMID 28640866, 2017). "Overweight and obesity are generally believed to be protective factors for BMD through mechanical loading and hormonal factors, including insulin, estrogen, and leptin." (PMID 28253896, 2017). "Further, MCP-1/CCR2-deficiency increased adiponectin expression, and improved systemic glucose homeostasis and insulin sensitivity; an effect that was mirrored by acute CCR2 antagonism in mice with established HFD-induced obesity." (PMID 29186929, 2017). "Serum concentrations of insulin, insulin-like growth factor-1 (IGF-1), leptin, and adiponectin were measured as obesity-related phenotypic markers." (PMID 28170448, 2017). "The endocrine–metabolic regulatory axis comprising growth hormone (GH), insulin and IGF1, which is drastically altered under extreme metabolic conditions such as obesity, also plays relevant roles in the development, modulation and homeostasis of the PG." (PMID 28244645, 2017). "This study demonstrated that curcumin not only exerted an anti-obesity effect but also reduced FBG level and improved insulin sensitivity in HFD-induced obese mice." (PMID 29291086, 2017). "Our multivariable analyses were adjusted for obesity (BMI), diet and physical activity, yet the differences between the South Asian and white participants remained for FPG and measures of insulin sensitivity and secretion." (PMID 28409212, 2017). "Fibroblast growth factor-21 (FGF-21) improves insulin sensitivity and lipid metabolism in obese or diabetic animal models and has been proposed as a potential therapeutic agent for treating T2DM, obesity, and their related complications." (PMID 28225059, 2017). "Compared with the lean subjects, the individuals with overweight/obesity had higher diastolic blood pressure(DBP),TG,fasting serum insulin and HOMA-IR levels." (PMID 28702069, 2017). "NAFLD and PCOS recognize the same dysmetabolic pathogenic background, i.e. obesity and IR.In this scenario, PCOS-related hyperandrogenism may contribute to liver disease by promoting systemic inflammation leading to impairment in insulin sensitivity and liver fibrogenesis." (PMID 29161258, 2017).
Obesity (continued). "Consistent with this concept, PAK1 signaling impairments in skeletal muscle have been correlated with obesity and T2D, indicating the significance of PAK1 in both insulin-dependent glucose uptake pathways in skeletal muscle." (PMID 29209279, 2017). "Second, depletion of either of them in ECs resulted in decreased white adipose tissue mass, adipocyte size and improvements of insulin and glucose tolerance responses following HFD-induced obesity." (PMID 28393867, 2017). "To examine the effect of CAST overexpression on HFD-induced glucose tolerance, we performed glucose tolerance test (GTT) and insulin tolerance test (ITT) during an early (5 or 6 weeks post diet) and late (15 or 16 weeks post diet) stage of obesity." (PMID 29089532, 2017). "This study assessed the effects of lipoic acid on brain insulin signaling, glucose metabolism, and synaptic plasticity in a mouse model of HFD-induced obesity." (PMID 28710347, 2017). "For ARHGEF4, we found that children with obesity more frequently showed gains (22.6%) as also observed for CPXCR1 (49.2%), whereas for INS losses occurred most frequently in obese children (25.7%)." (PMID 28428959, 2017). "It is well known that different populations exhibit differences in postprandial lipaemic responses; for example sex, obesity, age, fasting TAG and insulin sensitivity influence the postprandial response to a standard test meal." (PMID 27511058, 2017). "Fasting glucose and blood insulin levels were similarly elevated in mice fed a HFD compared to mice fed a ND, indicating the status of obesity-related hyperglycemia and hyperinsulinemia." (PMID 29116160, 2017). "Thereby, liver damage and VAT accumulation work synergistically to impair skeletal muscle regeneration in obesity by increasing FFA circulation, proinflammatory cytokines, and limiting promyogenic insulin actions on muscle." (PMID 28261159, 2017). "Our data showed that the subjects with overweight/obesity had higher insulin and HOMA-IR levels, suggesting that the subjects with overweight/obesity had obtained IR." (PMID 28702069, 2017). "Protein tyrosine phosphatase 1B (PTP1B) is a well-known inhibitor of insulin signaling pathways and inhibitors against PTP1B are being developed as promising drug candidates for treatment of obesity." (PMID 28492548, 2017). "We found that CNP overexpression increased energy expenditure, reduced mesenteric adipose tissue (MesWAT) hypertrophy, and improved insulin sensitivity and hepatic lipid metabolism during HFD-induced obesity." (PMID 28852070, 2017). "Prebiotic supplementation of obese animals (ob/ob mice, diet-induced obesity, obese Zucker or JCR:LA-cp rats) also decreased body weight gain, adipocyte size, adiposity, and insulin resistance." (PMID 29090088, 2017). "During normal development, late adult mice show evidence of the onset of obesity, including a twofold increase in WAT and BAT indexes, increased plasma triglyceride and insulin levels, and decreased glucose tolerance." (PMID 29038358, 2017). "Molecular studies have shown that insulin, insulin-like growth factor (IGF-1) axis, adipokines, sex-steroid hormones, and chronic low-grade inflammation are the main pathways linking obesity and colorectal neoplasia, including CRAs and CRC." (PMID 29079785, 2017). "Particularly, C646 improved insulin sensitivity in mice fed an HFD and significantly ameliorated hyperglycemia in ob/ob mice, making C646 is a potential agent for the treatment of obesity and T2D." (PMID 28743992, 2017). "The expression of TNF-α increases in the WAT of obese animals as well as that of human WAT due to obesity, and the expression level of TNF-α in WAT shows a significant positive correlation with body mass index (BMI) and blood insulin concentration." (PMID 28168013, 2017). "Immune cells of the innate and adaptive immune systems infiltrate insulin responsive tissues, such as the visceral adipose tissue (VAT) and with obesity incite inflammatory responses." (PMID 29270179, 2017).
Obesity (continued). "Interestingly, dietary intake of high amounts of butyrate has been reported to improve insulin sensitivity and counteract HF diet-induced obesity, but whether gut microbial synthesis can raise butyrate levels in circulation to the same degree remains questionable." (PMID 28390422, 2017). "In another study, when a MCP-1 knockout mouse was fed a HFD to the point of obesity, the infiltration of macrophage into WAT was controlled and insulin sensitively was increased in a more sensitive manner compared with that in a control mouse." (PMID 28168013, 2017). "For each SNP, the proportion was estimated using the traits (fasting levels of total and free IGF-I, IGFBP3, insulin, glucose, and HOMA-IR), after stratification by obesity status, level of PA, and exogenous E use." (PMID 29023587, 2017). "T2D, obesity and MTS are a heterogeneous group of metabolic disorders characterized by defects of both insulin secretion and insulin activity." (PMID 26728312, 2016). "Recently, studies demonstrate that obesity is strongly related to CRC, which is involved in several mechanisms, such as obesity-related insulin resistance, oxidative stress, adipocytokine production, and insulin-like growth factor-1 (IGF-1)." (PMID 27642602, 2016). "A total of 89% of the participants were overweight (with 69% obesity), 33% had hypertriglyceridemia, 44% had low plasma HDL-c and 77% had fasting plasma insulin ≥90 pmol/l." (PMID 27427488, 2016). "Since we have found that both insulin and leptin increase Sam68 expression in breast cancer cell lines, the hyperinsulinemia and hyperleptinemia that occur in obese women may contribute to the overexpression of Sam68 found in the tumours from patients with obesity-related breast cancer." (PMID 27415018, 2016). "CTe was orally administrated to diet-induced obesity (DIO) mice once daily for 3 weeks after which changes in glucose, insulin metabolism, and fat accumulation were examined." (PMID 26989693, 2016). "Remarkably, the same metabolic transformation does not occur in females, who despite corrected feeding behavior and normalized insulin levels remain physically inactive, have lower energy expenditure, compromised BAT and develop obesity." (PMID 26977396, 2016). "As TyG index quartiles increased, obesity-related parameters were aggravated and the mean HOMA-IR and insulin levels increased." (PMID 27682598, 2016). "Conversely, our study revealed that insulin can potentiate leptin-induced STAT3, a transcription factor critical to a major signaling pathway exerting anti-obesity effects of leptin." (PMID 27812350, 2016). "In this study, we demonstrated that HFD-induced obesity triggered TGF-β signaling, which downregulates insulin signaling in the fat body." (PMID 27484164, 2016). "Differently, levels of insulin and IGF-1 are commonly higher in subjects affected by age-related diseases or obesity than lean healthy subjects." (PMID 27899768, 2016). "Previous studies have demonstrated specific effects of the age, obesity, HFD, and gender on insulin sensitivity and skeletal muscle mitochondrial function." (PMID 26880072, 2016). "Men had higher TC, LDL-c, SBP, DBP and apo B-100, while women had higher mean body mass index (BMI) and a prevalence of obesity, higher HDL-c, fasting insulin and HOMA-IR." (PMID 27427488, 2016). "We examined the effects of insulin or FFA, both of which were systemically elevated in HFD-induced obesity." (PMID 27827416, 2016). "We studied the effect of maternal obesity and resistance training on femoral bone marrow (FBM) and vertebral bone marrow (VBM) insulin sensitivity in elderly women with the history of their mother’s obesity status." (PMID 27669153, 2016). "Conversely, ameliorating the low-grade inflammation companied with obesity by n-3 PUFA benefits obesity and its sequelae via modulating adipokines secretion and improving insulin sensitivity." (PMID 26339623, 2015).